ZEB1 (zinc finger E-box binding homeobox 1)
Diseases named in the same sentence as ZEB1 in open-access papers (continued):
Sharing a sentence is not in itself a finding about the gene and the disease.
tumor (continued). "Strong associations were found between ZEB1 and E-cadherin levels and critical clinical variables such as LNM, tumor stage, and grade, indicating the potential utility of these biomarkers as prognostic indicators for PTC." (PMID 40787244, 2025). "Immunohistochemical detection showed that circ-ZEB1 silencing suppressed Ki67 expression in tumor tissues, suggesting circ-ZEB1 downregulation inhibits NSCLC cell proliferation." (PMID 39802932, 2025). "Increased ZEB1‐ and vimentin‐positive tumor cells with decreased membrane E‐cadherin staining were also present in these tumors, indicating pEMT to be induced in tumor cells by stromal TGF‐β1." (PMID 40644310, 2025). "We studied the correlation of tumor invasiveness with ZEB1 status and vascular endothelial growth factor/its receptor (VEGF-A/VEGFR2) in UM cells, and also with melanocyte’s differentiation rate." (PMID 41226394, 2025). "Activation of STAT3 signaling plays a pivotal role in inducing ZEB1-mediated epithelial-mesenchymal transition (EMT) in various tumors, with STAT3 exerting a strong influence on the expression of ZEB1 in tumor cells." (PMID 40016707, 2025). "For example, miR-200c, which is frequently downregulated in TNBC, acts as a tumor suppressor by targeting ZEB1 and ZEB2, key regulators of epithelial-to-mesenchymal transition (EMT)." (PMID 41011238, 2025). "SOX2 can also induce epithelial-mesenchymal transition (EMT) by regulating ZEB1, N-cadherin, and other factors, thereby enhancing tumor cell migration and invasion and promoting metastasis." (PMID 41358198, 2025). "In a similar vein, USP18 was determined to bolster tumour proliferation, migration, and invasion by deubiquitinating ZEB1 and Snail1 and solidifying their expression." (PMID 39804798, 2025). "For instance, TIMP1 promotes RCC metastasis by inducing EMT, while CSN5 facilitates tumor progression through the stabilization of ZEB1, thereby enhancing EMT-mediated tumor spread." (PMID 40002717, 2025). "EMT promotes tumor cell detachment from the primary site, resistance to anoikis, and distant colonization by regulating key transcription factors (e.g., Snail, ZEB1, and Twist) and downstream signaling pathways (e.g., TGF-β, MAPK, and Wnt/β-catenin)." (PMID 40941019, 2025). "Our findings suggested that CCL2 and CCL22 from ZEB1-expressing alveolar macrophages increase CTL abundance to limit metastatic lung colonization of KPC tumor cells." (PMID 40595293, 2025). "The most studied ZEB protein is undoubtedly ZEB1, which has been shown to play multiple roles in regulating the aggressivity and chemoresistance of different tumor types." (PMID 41303618, 2025). "SPARC can also induce EMT by upregulating the expression of EMT regulatory transcription factors SNAI1/2 and ZEB1 thereby inducing changes in cellular phenotype to promote tumour progression." (PMID 39865173, 2025). "These miRNAs act as tumor suppressors by targeting ZEB1 and ZEB2, key regulators of epithelial-to-mesenchymal transition (EMT) and stemness." (PMID 41011238, 2025). "The fluorescence intensities of ZEB1, Twist, Slug, and Snail in the tumor tissues of the PPI treatment groups presented a notable decrease in comparison with those in the control group." (PMID 40429774, 2025). "Regarding ENO1, future studies with larger sample sizes are essential to elucidate its interaction with ZEB1 and its subcellular localization in tumor cells, as these factors provide significant information on tumor progression and prognosis." (PMID 40005870, 2025). "ZEB1 and inflammation are dynamically interconnected in a reciprocal regulatory loop within epithelial and tumor cells, where pro-inflammatory cytokines, such as TGF-β, enhance ZEB1 expression under inflammatory conditions." (PMID 41148802, 2025). "Our work provides a novel overview of genes regulating JAM-A expression and provides a rational approach of combining ZEB1 inhibition with reovirus therapy to target both CAFs and tumor cells in stroma-rich tumors such as PDAC." (PMID 41244268, 2025).
tumor (continued). "Further histological evidence, such as human-specific ZEB-1 staining, also confirmed effective tumor implantation at this early time point." (PMID 40855299, 2025). "In an MLL-AF9 oncogene-driven AML mouse model, short hairpin RNA (shRNA)-mediated Zeb1 knockdown reduced bone marrow infiltration in vivo, and in vitro studies showed impaired tumor cell invasion." (PMID 41357210, 2025). "In cancer ZEB1 is an epithelial-to-mesenchymal (EMT) transition activator, and the TCF4/ β-catenin complex induces ZEB1 to regulate tumor invasiveness." (PMID 40961119, 2025). "ZEB1 plays a fundamental role in tumour progression and confers a poorer clinical outcome in cancer; nevertheless, PI3K-targeted therapy can suppress the metastatic drive by ZEB1, representing a novel treatment target in nodBCC." (PMID 41373535, 2025). "On transcriptional levels, there was a trend towards higher levels of ZEB1 and Drp1 expression in tumor samples compared to adjacent healthy liver tissues." (PMID 40830586, 2025). "Regarding our findings, several hub genes, including ADAM12, MET, THBS2, ZEB1, and ZEB2, have been previously implicated in PDAC progression, tumor invasiveness, and epithelial–mesenchymal transition (EMT)." (PMID 40728965, 2025). "This loop encompasses eight miR-200 family binding sites that actively repress EMT, thereby influencing ZEB1’s involvement in tumor development." (PMID 38388432, 2024). "Mesenchymal tumor cells (344SQ and 393P ZEB1) were more sensitive to IFN-γ than epithelial tumor cells (344SQ miR-200 and 393P)." (PMID 39343796, 2024). "It was found that USP51 and constitutively photomorphogenic 9 signalosome subunit 5 promote EMT by stabilizing the expression of ZEB1, leading to increased tumor invasion and metastasis." (PMID 38449391, 2024). "Similar to our findings in subcutaneous models, EV tumors showed robust tumor regressions, whereas Zeb1/Snail OE tumors exhibited delayed but progressive growth following immunotherapy." (PMID 38378697, 2024). "ZEB1 is regulated by DUBs, which ultimately leads to enhanced tumor invasion and metastatic capacity." (PMID 38449391, 2024). "Increased levels of transcription factors like Snail, Twist1 and Zeb1 enhances the sensitivity of tumor cells to ferroptosis." (PMID 38469234, 2024). "Owing to the well-established tumour-promoting effects of Zeb1, our findings are of high tumour-biological and translational relevance." (PMID 39009641, 2024). "In line with this idea, we found that Zeb1/Snail OE rendered parental tumor cells resistant to killing by OT-I cells, whereas depletion of Zeb1 and Snail made Esc tumor cells more sensitive to T-cell killing." (PMID 38378697, 2024). "Significantly higher levels of phosphorylated STAT3, CD206 (a TAM marker in mice) and SIRPα were present in the tumours treated with exosomes with a high ZEB1 level than in those treated with exosomes with a low ZEB1 level." (PMID 38183060, 2024). "Previously, we have reported the tumour-based EMT score consisting of a combination of E-cad, β-cat, Snail, Zeb-1, and Fascin expression and the association of this score with the adverse clinical features and poor prognosis in Glasgow CRC patients." (PMID 38935747, 2024). "In conclusion, ZIP4 can promote EMT and induce tumor invasion and metastasis through ZEB1 and ITGA3." (PMID 39664563, 2024). "On this basis, we demonstrated that local ZEB1 expression in tumor tissues promoted IFIT1 + TANs infiltration." (PMID 38898490, 2024). "qRT-PCR confirmed that silencing of ESM1 decreased the expression of ESM1 and ZEB1 in tumor tissues." (PMID 38954708, 2024).
tumor (continued). "In pancreatic cancer, genetic depletion of the EMT transcription factor ZEB1 suppressed cancer stemness, metastatic colonization capacity, and phenotypic/metabolic plasticity of tumor cells." (PMID 38324529, 2024). "As a well-established EMT regulator, ZEB1 was shown to be vitally implicated in GINS1-induced cancer progression through promoting EMT and tumor metastasis via β-catenin signaling." (PMID 38913193, 2024). "ZEB1 can reconstruct the tumor microenvironment and plays a synergistic role as a multi-effect transcription factor." (PMID 38916621, 2024). "To further demonstrate ZEB1 as a downstream target of TRPS1 in tumor cell metastasis, we examined the effects of ZEB1 knockdown on migration, invasion and wound healing of TRPS1-MT cells." (PMID 39307879, 2024). "ZEB1 overexpression is found to mediate tumor resistance to MAPK inhibitors via driving the phenotype switch of melanoma cells." (PMID 39092293, 2024). "Treatment with exosomes derived from cells with ZEB1 overexpression significantly increased the size of the formed tumours, while the exosomes derived from ZEB1 knockdown cells had the opposite effect (both P < 0.05)." (PMID 38183060, 2024). "Subsequently, we conducted a comparative between the results of the WGCNA and COX regression analyses with the actual expression of tumor cells, validating the prognostic model and establishing the hub gene ZEB1 as a CRC prognostic factor." (PMID 39193340, 2024). "Glabridin inhibits EMT by upregulating epithelial markers (E-cadherin, occludin) and downregulating mesenchymal markers (vimentin, Zeb1), effectively reducing tumor metastasis." (PMID 39723390, 2024). "Further, ZEB1 plays a pivotal part in shaping the tumor microenvironment and maintaining functions that support macrophages associated with tumors." (PMID 39193340, 2024). "Results demonstrated that while ZEB1 overexpression alone heightened tumor invasiveness, subsequent Rosiglitazone treatment markedly reduced this effect, impacting tumor cell migration." (PMID 39258786, 2024). "In human OC, CCR2 expression alongside with TAM infiltration correlated with ZEB1 in tumor cells, leading to poorer prognosis." (PMID 38892394, 2024). "Of note, TGFβ signaling has been shown essential for the acquisition of classical myofibroblast phenotypes and in tumor cells, ZEB1 is a key mediator of TGFβ signaling." (PMID 38937629, 2024). "Taken together, our work provides evidence for the function of IFIT1 + TANs in PCC tumors and suggests that IFIT1 + TANs and ZEB1 + tumor cells play an important role in TME remodeling through multiple mechanisms of signaling crosstalk." (PMID 38898490, 2024). "To validate our findings, we further demonstrated that tumor cells not only transcriptionally upregulated ZEB1 but also downregulated SIAH1 upon exposure to NK cells." (PMID 38191418, 2024). "Analysis of the DEGs in TCGA tumours revealed that the miR-18a/low tumours expressed high levels of EMT master regulators-ZEB1 and ZEB2 and Matrix metalloproteinases, MMP2, MMP3, MMP10, MMP11, MMP13 and MMP17 (p < 0.05)." (PMID 38786043, 2024). "To explore the physiological role of FBXO11 and ZEB1 in vivo, we transplanted A549 cells into nude mice (Balb/c-nu/nu) with an immunodeficient system suitable for tumor transplantation and immunology research." (PMID 39409891, 2024). "During EMT conversion, activated Zeb1 increases the synthetic levels of PUFAs, which increases the levels of active lipid peroxides, enhancing the sensitivity of tumor cells to ferroptosis." (PMID 38469234, 2024). "Another study reported that ZEB1-expressing tumor cells drive the development of a suppressive immune microenvironment at the invasive front via the upregulation of arginase and PD-L1 during M2 macrophage polarization." (PMID 38191418, 2024). "Collectively, we demonstrate that ZEB1-dependent plasticity of CAFs suppresses anti-tumor immunity and promotes metastasis." (PMID 38937629, 2024).
tumor (continued). "MiR-200c-3p is a well-known tumor suppressor miRNA that inhibits tumor progression and metastasis in breast cancer by downregulating ZEB1 and ZEB2." (PMID 39372872, 2024). "By implementing an increase or decrease in ZEB1 function in a mouse model, the study found that ZEB1 regulates tumor growth by controlling the recruitment of CD8+ T cells in tumors." (PMID 38835341, 2024). "Immunohistochemistry was used to detect changes in ZEB1 expression in tumor tissues with miR-200a-3p overexpression and knockdown." (PMID 38916621, 2024). "ZEB1 and ZEB2 are associated with tumor progression and malignancy in human OC by regulating EMT interconversions." (PMID 39796130, 2024). "In other words, a Zeb1-induced, tumour progression-favouring mesenchymal state, which includes abundant incorporation of PUFAs into cancer cell membranes, comes with the price of an associated vulnerability—the high sensitivity to ferroptosis." (PMID 39009641, 2024). "miR-200c delivery also resulted in significant down-regulation of β-catenin, ZEB1, vimentin, and N-cadherin expression in the tumor." (PMID 39198318, 2024). "ZEB1 promotes CRC cell growth by recruiting the NuRD(MTA1) complex, and the ZEB1/NuRD(MTA1) complex transcriptionally represses glycolysis-associated tumor suppressor genes." (PMID 39193340, 2024). "ZEB1, vimentin, and N-cadherin are EMT markers, and their expression is associated with tumor invasive, proliferation, and drug resistance." (PMID 39198318, 2024). "Tumors with FBXO11 deletion showed significant local invasion, while the results for tumors with FBXO11 and ZEB1 double knockdown were similar to those of tumors with ZEB1 single knockdown, with clear tumor boundaries." (PMID 39409891, 2024). "It is well-established that the transcription factor ZEB1 plays a pivotal role in promoting tumor invasion and migration by orchestrating the epithelial-to-mesenchymal transition (EMT)." (PMID 39736693, 2024). "Because the primary tumor exhibited triple negativity, we investigated the effect of ZEB1 on the upregulation of Vim in a TNBC cohort and identified a strong correlation between ZEB1 and Vim expression." (PMID 39256881, 2024). "ZEB1 is critical for EMT and its overexpression is known to drive tumor progression, thus upregulating ZEB1 to mediate EMT and promote metastasis and chemoresistance." (PMID 39403602, 2024). "ZEB1 and ZEB2 are important transcription factors involved in the EMT process, which is associated with increased tumor invasiveness and chemoresistance." (PMID 39403602, 2024). "ZEB1 interacts with the tumor microenvironment, including immune cells, and exhibits varying degrees of radioresistance and drug resistance." (PMID 39409891, 2024). "ZEB1 is a transcription factor that promotes tumor invasion and metastasis through the regulation of genes that promote EMT." (PMID 38612604, 2024). "Zinc finger E-box binding homeobox 1 (ZEB1), a critical determinant of cellular destiny, tumor initiation, cancer cell adaptability, and metastatic spread across various malignancies, is considered a transcriptional repressor." (PMID 39193340, 2024). "Next, the expression levels of BRCC3, ZEB1, E-cadherin and vimentin in tumor tissues were detected via immunohistochemistry." (PMID 38449391, 2024). "As a master regulator of cellular EMT signaling, transcription factor ZEB1 is recognized as a core driver of tumor metastasis." (PMID 38965605, 2024). "Clinical data from TCGA also indicate that ZEB1 expression is correspondingly higher in patients with higher clinical stages or tumor grades, which is consistent with our experimental results." (PMID 38641065, 2024). "They further showed a positive correlation between RHBDL4 expression in tumor tissue and Zeb-1 expression, a downstream target of Wnt/β-catenin." (PMID 38464180, 2024).
tumor (continued). "In some cases such as the lymph node metastasis of oral NC, most of the cancer cells within the metastasis tumor expressed not only E-cadherin but also vimentin and ZEB1, showing a mixed epithelial–mesenchymal phenotype." (PMID 38724194, 2024). "ZEB1 orchestrates the transcription of genes in the control of several key developmental processes and tumor metastasis via the EMT." (PMID 38966180, 2024). "Another study revealed that USP39 has also a direct DUB activity towards the regulation of zinc-finger E-box-binding homeobox 1 (ZEB1), a key promoter of epithelial-to-mesenchymal transition that enhances tumour growth and metastasis." (PMID 38455765, 2024). "By creating EMT phenotypes and stem cell-like features in tumor cells, ZEB1 can play an important role in the development of BC." (PMID 38462658, 2024). "ZEB1 is a well-known transcription factor that plays a crucial part in tumor biology by driving cancer progression and metastization through the repression of E-Cadherin and consequent EMT promotion." (PMID 38254117, 2024). "Immunofluorescence staining and BODIPY detection, through flow cytometry, revealed a significant increase in lipid droplets within the tumor cells, following treatment with a ZEB1 activator and Rosiglitazone." (PMID 39258786, 2024). "The E3 ubiquitin ligase activity of TRIM26 targeting ZEB1 and to act as a tumor suppressor in HCC was studied before." (PMID 38260302, 2024). "The results demonstrated a robust enrichment of ZEB1 and HDAC1 on the promoters of CLDN7 and ANXA7, all of which are implicated in tumor suppression." (PMID 39193340, 2024). "The previous study showed that CDK4/6 inhibition facilitates ubiquitination of ZEB1, a key molecule in tumor metastasis, via suppressing activation of the deubiquitinase USP51." (PMID 38596406, 2024). "ZEB1, in particular, is highly expressed in various cancers and plays a crucial role in tumor progression and metastasis." (PMID 39409891, 2024). "This cytokine encourages the production of factors such as Zeb1 by tumor cells, promoting angiogenesis and fueling tumor growth." (PMID 39519376, 2024). "As transcription factors of E-cadherin, ZEB1 and slug bind to the E-cadherin promoter to suppress its transcription and trigger tumour cell dedifferentiation and spreading, which is the key step of the EMT process." (PMID 38429738, 2024). "The upregulation of ZEB1 expression has been observed to exhibit a positive correlation with elevated tumor grade and metastasis across various types of cancers." (PMID 39193340, 2024). "This highlights the key role of the ERK1/2 pathway and Zeb1 in driving both therapeutic resistance and tumor stemness in PLK1-driven tumors." (PMID 39451218, 2024). "The expression levels of ESM1 and ZEB1 in tumor tissues of AE treated group were decreased by qRT-PCR." (PMID 38954708, 2024). "Esc and Zeb1/Snail OE tumors expressed lower levels of gMDSC-recruiting cytokines and chemokines than parental and EV tumor cells, including G-CSF, GM-CSF, IL-1a, and CXCL2." (PMID 38378697, 2024). "A high expression in tumor tissues of Zeb1, and also of Twist, was found to positively correlate with tumor progression and a significantly reduced metastasis-free survival." (PMID 38247872, 2024). "We found that FGF7+/THBS1+ myofibroblasts, MS4A4A+ macrophages, and ZEB1+ endothelial cells were tumour‐enriched cell subtypes in MCA, contributing to MCA progression through crosstalk with MUC1+ cancer cells." (PMID 38778448, 2024). "Our comprehensive analyses revealed ZEB1 as a central TF that accelerates tumor progression by promoting cancer cell glycolysis." (PMID 39193340, 2024).